CXCL12 (C-X-C motif chemokine ligand 12)
Diseases named in the same sentence as CXCL12 in open-access papers (continued):
Sharing a sentence is not in itself a finding about the gene and the disease.
ovarian carcinoma (continued). "The ligand for CXCR4 is CXCL12, which can stimulate ovarian cancer cells migration in vitro." (PMID 22022379, 2011). "Subsequently, CXCR4 and CXCL12 expression in ovarian cancer have been confirmed by other studies." (PMID 20049170, 2010). "However, in consideration that 91% and 59% of ovarian cancers express CXCL12 and CXCR4, respectively, it was proposed that an overexpression of this chemokine system was present in ovarian malignant cells." (PMID 20049170, 2010). "In addition, it was also demonstrated that CXCL12 effects on ovarian cancer cell lines are mediated by EGFR transactivation through a mechanism involving the activity of cytosolic tyrosine kinases, belonging to the c-Src family." (PMID 20049170, 2010). "Besides the upstream signaling of HIF-1α, the downstream effectors of HIF-1α might also be involved in the ovarian cancer malignancy, namely, C-X-C motif chemokine ligand 12 (CXCL12) and C-X-C motif chemokine receptor 4 (CXCR4)." (PMID 36207479, 2023). "The CXCL-12-CXCR-4 axis also orchestrates the recruitment of TAMs via endothelial barrier into hypoxic tumor regions, and targeting CXCL-12-CXCR-4 axis alleviates tumor burden and metastatic susceptibility in breast, prostate, and ovarian cancer models by averting TAM infiltration." (PMID 33920168, 2021). "Importantly, the secretion of CXCL12 in ovarian cancer ascites was hindered by COX-2 inhibitors." (PMID 33271839, 2020). "Therefore, modulation of the CXCL12/CXCR4 axis in ovarian cancer could affect multiple aspects of tumor pathogenesis, including immune dysregulation." (PMID 31384667, 2019). "However, corroborating the high levels of CXCL12 in ascitic fluid that indicate poor survival with poor disease prognosis due to ascites presence, we can assume that quantifying CXCL12 levels in ascitic fluid might represent a good biomarker in ovarian cancer." (PMID 31703453, 2019). "Dysregulated expression of the chemokine ligand SDF-1 (stromal derived factor-1, or CXCL12), or its cognate receptor CXCR4 (C-X-C chemokine receptor type 4), is associated with higher grades and poorer prognosis in various human cancers, including ovarian carcinomas." (PMID 28938623, 2017). "Thus, angiogenesis in ovarian cancer may be potentiated by the interaction of CXCL12 produced by the cancer cells and CXCR4 expressed by the endothelial cells in hypoxic conditions." (PMID 24384839, 2013). "Thus, studying CXCR4/CXCL12 function in epithelial ovarian cancer, the choice of an incorrect cell controls could bring wrong conclusions." (PMID 20049170, 2010). "In addition, downregulation of CXCR4 and CXCL12 and inhibition of chemotaxis and chemoinvasion in breast and ovarian cancer cells toward CXCL12 are among of the biological effects of genistein likely through the inhibition of the estrogen dependent CXCL12 mRNA synthesis." (PMID 20049170, 2010). "Second, the omenta of HGSC patients produced higher levels of three cytokines, namely HGF, SDF-1a/CXCL12 and MCP-1/CCL2, known to mediate cell migration, invasion, proliferation and metastasis in ovarian cancer." (PMID 40076450, 2025). "CXCL12, also known as SDF-1 (stromal-derived factor 1), is a potent chemoattractant whose receptor CXCR4 is overexpressed on the surface of ovarian cancer cells." (PMID 40362280, 2025). "In a vitro experiment, the researchers established that tetrahydroxycurcumin prevents the spread and invasion of human ovarian cancer cells SKOV3 by regulating the expression of CXCR4 and CXCL‐12." (PMID 41179371, 2025). "Ovarian cancer chemokine landscape profiling revealed chemokines such as CCL2, CCL4, CCL5, CXCL10, and CXCL12 as potential candidates in ovarian cancer." (PMID 41424784, 2025). "CAFs-secreted CXCL12 induced EMT and cisplatin resistance in epithelial ovarian cancer though CXCR4/Wnt/β-catenin pathway." (PMID 39759028, 2024).
ovarian carcinoma (continued). "In ovarian cancer, the CXCR4-CXCL12 axis attracts monocytic myeloid-derived suppressor cells (MDSCs) to the tumor, with PGE2 inducing functional CXCR4 and CXCL12 expression." (PMID 39000453, 2024). "Nataša and group found that the tumor-associated inflammatory mediator prostaglandin E2 (PGE2) regulated CXCL12 production in malignant ascites of ovarian cancer patients, as well as CXCR4 expression on MDSC and its response to CXCL12." (PMID 37497001, 2023). "In ovarian cancer TME, CXCL12 is secreted by several cells and drives Tregs recruitment, inhibits leukocytes and facilitates M2 macrophage polarization, driving the TME toward an immunosuppressive status." (PMID 35406620, 2022). "Meanwhile, the chemokine landscape of ovarian cancer was found to be quite heterogeneous, because of different functions of known lymphocyte-recruiting chemokines in TME, such as CCL2, CXCL9, CXCL10, CXCL12, and CXCL16." (PMID 34386037, 2021). "Binding of the CXCR7 receptor to the ligand CXCL12 activates the p38 MAPK pathway to promote MMP-9 expression, thereby enhancing ovarian cancer cell invasion." (PMID 33829065, 2021). "The transcriptional levels of CXCL1, CXCL8, CXCL10, CXCL11, CXCL12, CXCL13, and CXCL14 were significantly elevated while CXCL3 was obviously reduced in ovarian cancer vs normal ovarian tissue." (PMID 33763130, 2021). "Our results showed that CXCL1, CXCL8, CXCL9, CXCL11, CXCL12, CXCL16, and CXCL17 were remarkably elevated in ovarian cancer compared to those in normal tissue." (PMID 33763130, 2021). "In ovarian cancer, tumor-related MSCs were able to induce resistance to hyperthermic intraperitoneal chemotherapy by activating the CXCL12-CXCR4 axis, and when the CXCL12/CXCR4 interaction was blocked, the cytotoxicity of hyperthermia was restored." (PMID 34736460, 2021). "In vitro stimulation of human normal fibroblasts with LPA (as well as with conditioned medium from an ovarian cancer cell line) converted these cells into CAFs that expressed αSMA, TGFβ1, TGFβ2, VEGFA, VEGFB, FAP, CXCL12 and IL-6." (PMID 34200030, 2021). "The CXCL12/CXCR4 pathway enhances metastasis, invasion, migration, and the proliferation of ovarian cancer." (PMID 34307366, 2021). "The CXCL12 peptide dimer was shown to inhibit migration, and upon increasing concentrations, induced cell death by mitotic catastrophe of CXCR4-expressing ovarian cancer cells." (PMID 34503058, 2021). "It is very plausible that this effect was associated with the higher secretion levels of several agents known to support ovarian cancer cell progression by these cells, such as CCL2, CXCL8, CXCL12, ICAM-1, IL-6, HGF, PAI-1, uPA, TGF-β1, and VEGF." (PMID 31086083, 2019). "The cross-talk between CXCL12-activated CXCR4 and EGFR was suggested to play an important role in cell proliferation signaling in ovarian carcinoma cell lines." (PMID 31703453, 2019). "Adding to this, metastatic fibroblasts are also the only cells expressing CXCL12, which along with CXCR4 play a pivotal role across many cancers, including ovarian cancer." (PMID 30383866, 2018). "TCDD was first shown to downregulate CXCL12 and CXCR4 expression in breast and ovarian cancer cells." (PMID 28261155, 2017). "A PGE2 controlled mechanism was recently described, inducing production of CXCL12 (SDF-1) in the tumor microenvironment and expression of CXCR4 on MDSCs, mediating their recruitment in human ovarian cancer." (PMID 26528286, 2015). "In the current study, we performed a comparative analysis on mRNA expression of CXCR3, CXCL-10 (IP-10), CXCR4, CXCL-12 (SDF-1α), IL-4 (interleukine-4) and IL-10 in tissues of benign and malignant ovarian tumors by the qRT-PCR method." (PMID 25999622, 2015). "Ko and colleagues demonstrated that ovarian cancer cells induce normal omental fibroblasts to express CAF markers and mitogenic factors such as IL-6 and chemokine (C-X-C motif) ligand 12 (CXCL12) that stimulated tumor cell proliferation." (PMID 24567915, 2014).
ovarian carcinoma (continued). "For example, a cross talk between CXCL12-activated CXCR4 and epidermal growth factor receptor (EGFR) has been proposed to link cell proliferation signals in ovarian carcinoma." (PMID 24384839, 2013). "CXCL12 signaling through CXCR4 promotes proliferation, invasion, and metastasis of ovarian cancer cells, all of which contribute to more aggressive disease." (PMID 23372646, 2013). "Chemokine CXCL12 and receptor CXCR4 have emerged as promising therapeutic targets for ovarian cancer, a disease that continues to have a dismal prognosis." (PMID 23372646, 2013). "To model the tumor microenvironment of ovarian cancer in vivo, we used spheroids of HeyA8-CXCR4-CBRN/Ar-CBC cells combined with equal numbers of HeyA8-CXCL12-GL cells, reproducing human ovarian cancer in which tumor cells secrete CXCL12 and/or express CXCR4." (PMID 23372646, 2013). "In this study, TMA was used to assess the expression of CXCL12 and CXCR4 in relation to clinico-pathological characteristics and overall survival of 289 ovarian cancer patients." (PMID 22415233, 2012). "In epithelial ovarian cancer (EOC), CXCL12 enhances tumor angiogenesis and contributes to the immunosuppressive network." (PMID 21410972, 2011). "In vitro studies directly demonstrated that, in the presence of CXCL12, CXCR4 controls both ovarian cancer cell proliferation and migration, through the activation of the ERK1/2 and Akt pathway." (PMID 20049170, 2010). "For instance, trimethylation at H3K27 represses the production of CXCL9 and CXCL10 in ovarian cancer, establishing an immune-suppressive TME, while DNMT1 is responsible for the decreased CXCL12 in osteosarcomas, resulting in reduced CTL recruitment at the cancer site." (PMID 39000359, 2024). "Moreover, with concomitant high CXCL12/CD66b TIC density, it is an independent favorable predictor of recurrence-free survival in patients with ovarian carcinoma." (PMID 37966614, 2023). "In ovarian cancers specifically, CAFs can induce angiogenesis through the secretion of IL-6, COX-2, and CXCL1, while ovarian cancer cells are reported to induce CAFs to secrete CXCL12, IL-6, and VEGF-A expression via HOXA9, leading to angiogenesis." (PMID 36672620, 2023). "In addition, the CXCL12/CXCR4 biological axis plays an important role in the progression of several cancers, including ovarian cancer and squamous cell carcinoma." (PMID 35893797, 2022). "C-X-C motif chemokine ligand 12 (CXCL12), C-X-C motif chemokine receptor 4 (CXCR4), and CXCR7 can influence the development of endometriosis, Asherman’s syndrome, endometrial cancer, and ovarian cancer." (PMID 36309699, 2022). "However, there are different results showing that CXCR4/CXCL12 axis promotes EMT and is a potential target of ovarian cancer progression." (PMID 33829065, 2021). "CXCR7 does not play a key role in EMT, but CXCL12/CXCR4 axis is a potential target for preventing ovarian cancer progression." (PMID 33829065, 2021). "Additionally, it was shown that CXCL12 acts synergistically with VEGF, which induces angiogenesis in human ovarian cancer, but also supports angiogenesis after ovulation." (PMID 32708880, 2020). "In CAOV-3 cells, CXCL12 and its receptor CXCR4 stimulated the secretion of integrin β-1 and vascular endothelial growth factor-C (VEGF-C), indicating the involvement of this receptor in the stimulation of tumor vasculature in ovarian cancer." (PMID 31703453, 2019). "The concomitant increased production of CXCL12, IL6, and VEGFA by CAFs within the tumor microenvironment could enable peritoneal metastasis of ovarian cancer via induction of the EMT program." (PMID 30380628, 2018). "Moreover, several soluble factors of mesothelial origin have been found to stimulate other vital elements of ovarian cancer cell progression, including proliferation (CXCL8/IL-8, IL-6), migration (CXCL12/SDF-1, HA), and invasion (LPA)." (PMID 28956065, 2018).
ovarian carcinoma (continued). "Data from the experiments conducted by Hall and Korach also pointed to the mitogenic potential of BPA, genistein and 2,2-bis(p-hydroxyphenyl)-1,1,1-trichloroethane (HPTE) in ovarian cancer cells, which was regulated via ER-mediated expression of the chemokine CXCL12 (stromal cell-derived factor-1)." (PMID 26831296, 2015). "Meanwhile, CXCL12 and VEGF were synergized in facilitating angiogenesis of ovarian cancer." (PMID 25887589, 2015). "Our preliminary study results showed a high expression of CXCR4 and CXCL12 in ovarian cancer tissues, but no expression in normal ovarian epithelial cells." (PMID 24765180, 2014). "Also, the chemokine CXCL12 activates the chemokine receptor CXCR4 on endothelial cells, which promotes endothelial cell migration and proliferation in ovarian cancer cells." (PMID 24259307, 2013). "CXCL12 also acts on tumor cell proliferation and survival and, through its main receptor CXCR4, governs the migration of malignant cells and their invasion of the peritoneum, a major route for ovarian cancer spread." (PMID 21410972, 2011). "In this same ovarian cancer model, IL-2 treatment was shown to up-regulate CCR4 as well as CXCR4, which further enhanced the ability of Treg to migrate to the tumor microenvironment based on its elevated levels of the Treg ligands CCL22 and CXCL12." (PMID 22112546, 2011). "In vitro, CXCL12 induces cell migration and invasion of the IGROV ovarian cancer cell line." (PMID 20049170, 2010). "In ovarian cancer, CXCR4 was detected among 681 hypo methylated-upregulated genes while PTEN, and FOXO-1 were mentioned among the hypermethylated repressed genes and in vascular smooth muscle cell (SMC), vascular injury increased PTEN/AKT signalling through CXCL12- HIF-1alpha." (PMID 38704478, 2024). "Thus, evaluation of genomic data has identified a number of clinical associations of signaling loops established by polypeptide ligands and their receptors in solid tumor tissue of advanced ovarian cancer, including TGFβ, PDGF, VEGF, ephrin, CXCL12, and CCL chemokines." (PMID 28275576, 2017). "In effect, TNFα can amplify the CXCL12 signal, and therefore neutralising TNFα, neutralising CXCL12, antagonising CXCR4 or inhibiting NF-κB may be an effective therapy for ovarian cancer." (PMID 22415233, 2012). "Thus, a “cross-talk” between CXCL12/CXCR4 and EGFR intracellular pathways may link signals of cell migration and proliferation in ovarian cancer." (PMID 20049170, 2010). "However, the specific regulation and functions of the different CXCL12 isoforms in human cancers remained unknown and have never been investigated in ovarian cancers." (PMID 29535360, 2018). "Importantly, it has been shown that disruption of the CXCR4/CXCL12 axis using CXCR4-specific RNAi or a small molecule inhibitor of CXCR4 AMD3100 led to a decreased tumor vessel density and markedly reduced tumor angiogenesis in a FVB/NJ immunocompetent model of ovarian cancer." (PMID 24384839, 2013). "Using female healthy donors with no history of ovarian cancer, we were also able to detect levels of CCL2, CCL4, CCL5, CXCL10 and CXCL12." (PMID 41424784, 2025). "Previous retrospective studies have reported the prognostic value of CXCL12 in 289 ovarian cancer patient as evaluated through tissue microarray, while a small study (44 EOC with a median 37 months follow-up) showed no prognostic meaning for CXCL12." (PMID 35406620, 2022).
leukemia (150 papers, 2010 to 2026). A malignant (clonal) hematologic disorder, involving hematopoietic stem cells and characterized by the presence of primitive or atypical myeloid or lymphoid cells in the bone marrow and the blood. "Previous studies found that the interaction between leukemia cells and the bone marrow hematopoietic microenvironment is a critical cause of chemotherapy resistance and disease recurrence, with the CXCL12/CXCR4 axis playing a pivotal role in this interaction." (PMID 40427609, 2025). "Although CXCL12 is normally associated with migration, in leukemia it has been shown to induce a quiescent state in CSCs, as well as resistance against tyrosine kinase inhibitors." (PMID 33530455, 2021). "With ongoing or chronic stress, such as in mice with leukemia, most stromal cell populations are diminished, with loss of expression of quiescence-promoting genes (Cxcl12, Angpt1, Vcam1) in Lepr+ AdipoCAR cells." (PMID 34368155, 2021). "The prognostic value of CXCL12/CXCR4 axis in leukemia has been studied to push forward risk-stratified therapeutic strategies." (PMID 34246314, 2021). "Aberrant CXCR4/CXCL12 signaling is associated with a variety of pathophysiological conditions including cancer metastasis, enhanced tumor growth, chronic inflammation, leukemia and altered immune responses." (PMID 32994431, 2020). "Signals from the CXCL12-chemokine receptor 4 (CXCR4) axis have been shown to act as critical mediators in interactions between leukemia cells and the microenvironment, which are the major cause of chemotherapy resistance and disease relapse in AML11,12." (PMID 31434952, 2019). "According to some studies, FLT3-ITD mutations enhance leukemia cell chemotaxis toward CXCL12, thus providing a drug resistance mechanism underlying the poor effect of FLT3-ITD antagonists." (PMID 31434952, 2019). "Thus, loss of Cxcl12 expression in ECs and MPCs is dispensable for leukemia development." (PMID 32460032, 2020). "Our findings indicate that both TCL1 and ROR1xTCL1 leukemia cells possess invasive capabilities in response to CXCL12." (PMID 40295829, 2025). "Treatment with lenalidomide, an immunomodulatory anticancer drug, inhibits STAT3Y705 phosphorylation induced with IL-10 in healthy T cells, reversing the T-cell dysfunction induced with CLL, indicating the significance of CXCL12/CXCR4 in leukemia treatment." (PMID 38920657, 2024). "ARC upregulated IL1β in AML cells and increased the levels of CCL2, CCL4, and CXCL12 in MSCs by activating the NFκB pathway, thereby promoting the migration and adhesion of leukemia cells to MSCs." (PMID 39351758, 2024). "In the same way, we observed that leukaemia‐derived sEVs downregulated the expression of various genes (CXCL12, ANGPT1, COL1A1 and SCF) in BM‐MSCs, vital to maintaining normal haematopoiesis in BMM." (PMID 38499475, 2024). "Multiple studies have demonstrated that within leukemia, the CXCL12/CXCR4 axis plays a pivotal role in maintaining the interactions between leukemia cells and the bone marrow niche." (PMID 38920657, 2024). "The similar downregulation of CXCL12 expression was recently observed in bone marrow derived LEPR + MSCs in murine leukemia." (PMID 38281962, 2024). "CXCR4 interacts with CXCL12 (CXC motif chemokine 12)/Stromal cell-derived factor-1 (SDF-1), that is a chemokine with a critical role for cells escaping from thymus to bone marrow, leukemia initiating cells and trans-endothelial migration." (PMID 36624522, 2023). "This drug blocks CXCR4 and opposes CXCL12 stimulation of chemotaxis and cell proliferation pathways in leukemia cells." (PMID 38313431, 2023). "An earlier study demonstrated the formation of dense MSC/leukaemia progenitor clusters within the BM was also Cxcl12-driven, indicating that leukemic cells home towards a Cxcl12-rich niche." (PMID 36780103, 2023).